MIR8071-2 (microRNA 8071-2)
Synonyms: hsa-mir-8071-2
Gene: MicroRNA gene on chromosome 14 (105,640,168 to 105,640,232, forward strand). Ensembl gene ENSG00000277030.
Homologues: Paralogues in human: MIR8071-1 (100% identical).